FCGR2A (Fc gamma receptor IIa)
Diseases named in the same sentence as FCGR2A in open-access papers (continued):
Sharing a sentence is not in itself a finding about the gene and the disease.
pneumonia (5 papers, 2016 to 2023). An acute, acute and chronic, or chronic inflammation focally or diffusely affecting the lung parenchyma, caused by an infection in one or both of the lungs (by bacteria, viruses, fungi, or mycoplasma.). "Upon pooling a total of 1332 cases and 5428 controls from thirteen studies, no strong evidence was found to support a significant association between FCGR2A rs1801274 and overall pneumonia risk." (PMID 32252656, 2020). "FCGR2A rs1801274 was reported to be significantly associated with the risk of severe pneumonia in A/H1N1 influenza infection, bacteremic pneumococcal pneumonia infection, and the severity of community-acquired pneumonia." (PMID 32252656, 2020). "Owing to data limitations, more available evidence is required to further clarify the genetic relationship between FCGR2A rs1801274 and pneumonia susceptibility." (PMID 32252656, 2020). "Here, for the first time, we carried out a meta-analysis and TSA test to comprehensively evaluate the genetic influence of FCGR2A rs1801274 in the susceptibility to clinical pneumonia." (PMID 32252656, 2020). "The inconclusive result of the genetic influence of FCGR2A rs1801274 on the susceptibility to clinical pneumonia has been observed in previous studies." (PMID 32252656, 2020). "In contrast, in intensive care unit patients with a diagnosis of invasive Streptococcus pneumoniae infection (202 with pneumonia and 55 with meningitis), the GG genotype (guanine) of the FCGR2A His131Arg polymorphism exerted a protective effect (OR 0.32)." (PMID 27267995, 2016). "The results showed that 36.6 % of the patients with severe pneumonia were homozygous for allele A of the rs1801274 variant of the FCGR2A gene, which encodes a histidine (His) at position 131 of the protein, while only 13.2 % of the contacts who did not develop the disease carried this variant." (PMID 27267995, 2016). "Therefore, this is the first pooling analysis that has been conducted to assess the potential association between FCGR2A rs1801274 and overall pneumonia risk and was carried out according to PRISMA (preferred reporting items for systematic reviews and meta-analyses) guidelines." (PMID 32252656, 2020). "Research on the FCGR2A gene is related to other inflammatory diseases, such as chronic periaortitis or severe pneumonia in A/H1N1 influenza infection." (PMID 35629038, 2022). "Herein, we collected currently published data to comprehensively evaluate the impact of the FCGR2A (Fc fragment of IgG receptor IIa) rs1801274 and MUC5B (mucin 5B, oligomeric mucus/gel-forming) rs35705950 variations on susceptibility to pneumonia diseases." (PMID 32252656, 2020). "Analyses of the previous thirteen case–control studies did not reveal a significant association between FCGR2A rs1801274 and overall pneumonia risk." (PMID 37896870, 2023). "MUC5B rs35705950, but not FCGR2A rs1801274, increases susceptibility to clinical pneumonia, especially to idiopathic pulmonary fibrosis, in both the Caucasian and Asian populations." (PMID 32252656, 2020). "No prior meta-analysis regarding the genetic role of FCGR2A rs1801274 in pneumonia susceptibility has been reported, and studies have reported different findings." (PMID 32252656, 2020). "After database retrieval and publication selection, we excluded reports of potential pneumonia-associated gene variation without enough or updated data, and finally focused on two variants, namely, FCGR2A rs1801274 and MUC5B rs35705950." (PMID 32252656, 2020). "Although FCGR2A rs1801274 was not identified in any genome-wide association study (GWAS) of pneumonia, we observed a positive association between FCGR2A rs1801274 and the risk of pneumonia." (PMID 32252656, 2020). "FCGR2A rs1801274 and MUC5B rs35705950 were selected due to the research status of pneumonia-related variations and the novelty of the data analysis." (PMID 32252656, 2020).
pneumonia (continued). "However, our TSA test data showed that the cumulative Z-curve did not totally reach the conventional boundary and required information size, suggesting the requirement for a larger sample size to confirm the negative association between FCGR2A rs1801274 and pneumonia risk." (PMID 32252656, 2020).
tuberculosis (5 papers, 2021 to 2023). A chronic, recurrent infection caused by the bacterium Mycobacterium tuberculosis. "We performed cluster analysis for the top 5 KEGG pathways to explore the association of genes such as LBP, CSF3, and FCGR2A with leishmaniasis, hematopoietic cell, strain, tuberculosis, and osteoclast differentiation." (PMID 33973530, 2021).
cryptococcosis (4 papers, 2008 to 2020). An acute or chronic, localized or disseminated infection by Cryptococcus neoformans. "A relationship between common functional genetic polymorphisms of the low-affinity Fc gamma receptor genes, FCGR2A, -3A, and -3B, and the risk of cryptococcosis in HIV-uninfected patients was recently reported." (PMID 18439357, 2008). "Meletiadis and colleagues genotyped FCGR2A 131H/R, FCGR3A 158F/V and FCGR3B NA1/NA2 in 103 cryptococcosis patients and 395 healthy controls." (PMID 22879986, 2012).
glioblastoma (4 papers, 2021 to 2025). The most malignant astrocytic tumor (WHO grade IV). "For instance, macrophages could be co-cultured with glioblastoma cell lines after knockout of signature genes (e.g., FCGR2A) to evaluate M2 polarization and observe changes in tumor cell biology." (PMID 40438577, 2025).
myocardial infarction (4 papers, 2010 to 2023). Gross necrosis of the myocardium, as a result of interruption of the blood supply to the area, as in coronary thrombosis. "Similar to the association of the rs1137101 gene polymorphism with myocardial infarction, the gene polymorphism of FCGR2A has also been confirmed to be associated with susceptibility to IS in people of different races." (PMID 37268894, 2023). "For instance, in a recent study, there was variation in the expression of the FCGR2A gene in the platelets after onset of myocardial infarction." (PMID 34285919, 2021).
neuroblastoma (4 papers, 2021 to 2024). Neuroblastoma (NB) is the most common solid, extracranial childhood tumor. "Notably, TAMs in high-risk neuroblastoma tissues highly expressed the macrophage-activating Fcγ receptor genes FCGR2A and FCGR3A, and therefore, antibody-mediated approaches are plausible for treating high-risk neuroblastoma patients." (PMID 38920727, 2024). "In the autologous setting, we have previously demonstrated that neuroblastoma patients with high-affinity FCGR2A, -3A and stimulatory KIR2DS2 show higher levels of ADCC and improved event-free survival." (PMID 34367149, 2021). "In neuroblastoma, neutrophils are recognized as a key effector of GD2 antibody therapy, mediating the eradication of opsonized cells via Fc gamma receptor IIa (FcγRIIa) binding." (PMID 39668192, 2024). "In addition, among Fcγ receptor genes, FCGR2A and FCGR3A, encoding activating receptors, are expressed at relatively high levels in high-risk neuroblastoma tissues, suggesting the potential roles of these FCGRs in macrophage-mediated anti-high-risk neuroblastoma immunity." (PMID 35525858, 2022). "In contrast to the LTI study, in our cohort, haplo HSCT using donors with high affinity FcGR3A or FcGR2A did not have any impact on event-free survival and overall survival in neuroblastoma Stage IV relapsed patients with subsequent GD2 targeted ch14.18/CHO antibody therapy." (PMID 34367149, 2021).
sarcoidosis (4 papers, 2017 to 2023). Sarcoidosis is a multisystemic disorder of unknown cause characterized by the formation of immune granulomas in involved organs. "Additionally, the presence of higher IC-binding variants of FCGR2A and FCGR3B genes in individuals with advanced stages of SA vs. TB patients, can help to predict if sarcoidosis will progress to a more severe disorder and serve as a marker of SA prognosis." (PMID 37174624, 2023). "Therefore, we have analyzed polymorphism of these genes in our SA patients and revealed that, in contrast to polymorphism of FCGR2B and FCGR3B, polymorphism of FCGR2A, FCGR2C and FCGR3A may contribute to immunocomplexemia present in sarcoidosis." (PMID 28472129, 2017). "We have found a lack of association between copy number of FCGR2A, FCGR2B, FCGR2C, FCGR3A, FCGR3B genes and risk of development of sarcoidosis in our patients." (PMID 28472129, 2017).
anemia (3 papers, 2012 to 2024). A reduction in the number of red blood cells, the amount of hemoglobin, and/or the volume of packed red blood cells. "Moreover, FCGR2A-131 H/H and FCGR2A-131 H/R carriers have an increased risk of anemia, hypogammaglobulinemia and sepsis post-rituximab treatment compared to R/R homozygotes." (PMID 39459523, 2024).
cerebral malaria (3 papers, 2012 to 2020). A sequestration of Plasmodium falciparum in the brain, which can cause coma and/or seizures. "Association studies based on Polymerase Chain Reaction-Sequence Specific Primer (PCR-SSP) data of FCGR2A and FCGR3B have found individuals carrying the NA2 allotype in combination with FcγRIIA-166H have an increased risk of developing cerebral malaria and severe malarial anaemia." (PMID 23049979, 2012).
clear cell carcinoma of the kidney (3 papers, 2021 to 2024). "As revealed by the GEPIA website, FCGR2A level in partial cancer tissues was comparatively higher than the adjacent normal tissues, including carcinoma of bile duct, esophagus carcinoma, clear cell carcinoma of kidney, and gastric cancer." (PMID 34285919, 2021).
giant cell arteritis (3 papers, 2006 to 2017). "In addition, a genetic association between the FCGR2A/FCGR3A polymorphism and giant cell arteritis (GCA) has been previously identified in a small cohort from Spain." (PMID 27769046, 2017).
glioma (3 papers, 2021 to 2025). A benign or malignant brain and spinal cord tumor that arises from glial cells (astrocytes, oligodendrocytes, ependymal cells). "Collectively, the function of these genes in tumors, especially VAMP8 and FCGR2A in gliomas, has been fully demonstrated." (PMID 34880206, 2021). "Using five existing glioma cell lines in the research group to carry out qRT-PCR, it was found that FCGR2A was expressed at a relatively high level in LN18 and T98G cells, whereas EHD2 was expressed at a high level in U251 and SNB19 cells." (PMID 33875619, 2021). "Silencing FCGR2A expression suppressed glioma proliferation, migration and invasion." (PMID 34880206, 2021). "Subsequent cell function test results showed that inhibition of FCGR2A or EHD2 significantly represses proliferation, migration, and invasion of glioma cells, and reduces the expression of mesenchymal marker genes." (PMID 33875619, 2021). "The remaining two genes, FCGR2A and EHD2, have not been studied in gliomas." (PMID 33875619, 2021).
lung carcinoma (3 papers, 2012 to 2024). "Recent studies have reported that the polymorphism of FCGR2A expression is associated with an increased risk of lung cancer." (PMID 35962453, 2022). "In some studies, FCGR2A-rs1801274 was found to be associated with an elevated risk of lung cancer." (PMID 38237211, 2024).
lupus nephritis (3 papers, 2016 to 2025). Glomerulonephritis in the context of systemic lupus erythematosus. "Our results emphasize an association between FCGR2A-131R and lupus nephritis with a distinctive FCGR polymorphism distribution in an indigenous African Caribbean population, confirming the important variation in the FCGR locus depending on ethnic origin." (PMID 40728959, 2025). "We conducted a detailed analysis of the association between FCGR2A, FCGR2B, FCGR3A and FCGR3B polymorphisms and lupus nephritis." (PMID 40728959, 2025). "Our findings revealed a significant correlation between FCGR2A-131R and lupus nephritis in our African Caribbean population." (PMID 40728959, 2025).
parasitemia (3 papers, 2015 to 2023). "Indeed, this allele, combined with FCGR2A-131R and FCGR3B-NA1, was indicated to be associated with high levels of parasitemia in children from western Kenya, while the FCGR2A-131R/FCGR3A-158F/FCGR3B-NA2 haplotype was associated with susceptibility to severe malarial anemia (SMA)." (PMID 33281811, 2020).
psoriasis (3 papers, 2015 to 2025). An autoimmune condition characterized by red, well-delineated plaques with silvery scales that are usually on the extensor surfaces and scalp. "Comparison between patients with type I psoriasis and patients with type II psoriasis revealed significant associations for the following genes: FCGR2A, TNFR1, CD226, PSORS6, TNFAIP3, HLA-C, TNF-α, and CCHCR1." (PMID 26613086, 2015). "Ours is the first study to identify an association between FCGR2A, TNFR1, CD226, TNFAIP3, and CCHCR1 and age at onset of psoriasis." (PMID 26613086, 2015). "Moreover, rs1801274 in FCGR2A and rs6920220 in TNFAIP3 have not been studied in patients with psoriasis according to age of onset." (PMID 26613086, 2015).
Sepsis (3 papers, 2022 to 2024). Sepsis is defined as life-threatening organ dysfunction caused by a dysregulated host response to infection. "Therefore, FCGR2A may be closely associated with sepsis severity, but it still needs to be confirmed by a multi-center and extensive sample study." (PMID 36532072, 2022). "The variant FCGR2A-p.166Arg may be a marker of genetic susceptibility to sepsis." (PMID 36532072, 2022). "Also, Solé-Violán J found that patients with bacteremic PCAP (B-PCAP) were associated with sepsis severity and homozygosity for FCGR2A-p.166His predisposes B-PCAP, which suggests that the variant FCGR2A-p.166His may be related to sepsis severity." (PMID 36532072, 2022).
Takayasu arteritis (3 papers, 2015 to 2018). A rare inflammatory large-vessel vasculitis primarily affecting the aorta and its major branches, but also other large vessels, causing stenosis, occlusion, or aneurysm. "A recent genome-wide association study revealed that the FCGR2A/FCGR3A genes confer susceptibility to Takayasu arteritis, another chronic large-vessel vasculitis." (PMID 30037347, 2018). "The same study also suggested a link between Takayasu arteritis and the FCGR2A/FCGR3A locus." (PMID 26839728, 2015).
Venous thrombosis (3 papers, 2020 to 2022). Formation of a blood clot (thrombus) inside a vein, causing the obstruction of blood flow. "PF4 interacted with the Fc-gamma receptor IIA (FcγRIIa) of platelets and then activated the platelets to enter a hypercoagulable state, leading to increased PF4 release and promoting arterial and venous thrombosis, which ultimately triggers VITT." (PMID 36419624, 2022).
Arthritis (2 papers, 2005 to 2023). Inflammation of a joint. "To explore the relationship between functional polymorphisms in FcγRs (FCGR3A-158V/F and FCGR2A-131H/R) and arthritis in individuals positive for anti-GPI antibodies, we evaluated these individuals with respect to FCGR genotype." (PMID 16277670, 2005).
B cell lymphomas (2 papers, 2015 to 2022). "In a small study of patients with various low-grade B-cell lymphomas, two polymorphisms in FCGR2A (previously studied in HL) were found at different frequencies between EBV-positive and EBV-negative low-grade B-cell lymphoma." (PMID 25430668, 2015). "The studies linking this gene to EBV-positive B-cell lymphoma have both been relatively small and have examined a disparate collection of classical HL and non-HL, non-BL, making it difficult to draw conclusions on the role of FCGR2A in EBV susceptibility and disease." (PMID 25430668, 2015).
bladder cancer (2 papers, 2022 to 2025). "Studies have shown that blocking FCGR2A or knocking down IgG in various cancers, including hepatocellular carcinoma (HCC), cervical, and bladder cancers, reduces platelet activation and subsequent metastasis." (PMID 41226816, 2025).
cutaneous malignant melanoma (2 papers, 2020 to 2023). "Also, the immune regulation pathway that FCGR2A participates in was reported to show significant association with cutaneous malignant melanoma risk." (PMID 33392203, 2020).
dementia (2 papers, 2022 to 2023). Loss of intellectual abilities interfering with an individual's social and occupational functions. "Seventeen proteins had more than a 50% difference between subjects with dementia and controls, including VIM (2.2 fold increase), NTproBNP (2.2 fold increase), CHIT1 (2.2 fold increase), NEFL (1.7 fold increase), ENPP7 (1.6 fold decrease), and FCGR2A (1.5 fold decrease)." (PMID 37175824, 2023).
diabetes (2 papers, 2021 to 2023). "A final multivariable model found three proteins (Contactin-5 [CNTN5], Low affinity immunoglobulin gamma Fc region receptor II-a [FCGR2A], and Complement factor B [CFB]) associated with incident CVD after adjustment for diabetes (AUC = 0.82)." (PMID 33441605, 2021).
head and neck squamous cell carcinoma (2 papers, 2021 to 2024). A squamous cell carcinoma that arises from any of the following anatomic sites: lip and oral cavity, nasal cavity, paranasal sinuses, pharynx, larynx, and salivary glands. "The results indicated that the expression of FCGR2A was significantly upregulated and acted as a risk factor in most types of cancers, such as lung adenocarcinoma (LUAD) and head and neck squamous cell carcinoma (HNSCC)." (PMID 38237211, 2024).
nephritis (2 papers, 2007 to 2025). Inflammation of renal tissue. "A further analysis within patients with LN underlined a significant difference in the distribution of the FCGR2A-R131H when compared to those without nephritis." (PMID 40728959, 2025).
Nephropathy (2 papers, 2006 to 2025). A nonspecific term referring to disease or damage of the kidneys. "Both global SLE phenotype and renal disease in patients with IgG2 anti-C1q autoantibodies have been associated with alleles of FCGR2A." (PMID 17076550, 2006). "Interestingly, the FCGR2A-131R allele is associated with the poor progression of nephropathy associated with IgG deposition." (PMID 40728959, 2025).
Obesity (2 papers, 2020 to 2025). Accumulation of substantial excess body fat. "Our study establishes FCGR2A as a pivotal interface between metabolic inflammation and ccRCC progression, reconciling the paradoxical association of obesity with both increased cancer risk and enhanced immunotherapy responses." (PMID 41199823, 2025). "Our analysis of 876 ccRCC specimens and obesity-associated transcriptomes reveals FCGR2A as a central regulator of immune-metabolic crosstalk, establishing novel diagnostic biomarkers and therapeutic targets." (PMID 41199823, 2025). "This study establishes a novel FCGR2A-centered paradigm for understanding the molecular interplay between ccRCC and obesity, providing clinically validated biomarkers and actionable therapeutic targets." (PMID 41199823, 2025). "Future studies should employ spatial transcriptomics to map FCGR2A+ myeloid cell localization and develop humanized mouse models with diet-induced obesity." (PMID 41199823, 2025). "This explains the elevated FCGR2A signal in bulk RNA-seq of obese patients and provides mechanistic insight into the ‘obesity paradox’ in immunotherapy response." (PMID 41199823, 2025). "The role of FCER1 G, TYROBP, CXCL16 and FCGR2A in obesity has been discussed previously." (PMID 32684073, 2020). "Methotrexate and aspirin demonstrated multi-target activity against myeloid activation (FCGR2A, ITGB2), aligning with recent obesity-cancer immunomodulation studies." (PMID 41199823, 2025).
osteoporosis (2 papers, 2022 to 2025). A condition of reduced bone mass, with decreased cortical thickness and a decrease in the number and size of the trabeculae of cancellous bone (but normal chemical composition), resulting in increased fracture incidence. "In this study, we identified five key genes related to the circadian rhythm in osteoporosis (RAB5C, ECE1, FLT3, FCGR2A, and APPL1) using bioinformatics and machine learning approaches." (PMID 40642528, 2025).